CXCR6 (C-X-C motif chemokine receptor 6)
Diseases named in the same sentence as CXCR6 in open-access papers (continued):
Sharing a sentence is not in itself a finding about the gene and the disease.
colitis (10 papers, 2013 to 2026). Inflammation of the colon. "CXCR6 deficiency seems to be compensated by other chemokine receptors in this experimental colitis model." (PMID 23840334, 2013). "However, in the CD45RBhigh T-cell-transfer colitis model, we show that CXCR6-deficient CD4+ T cells retain the ability to induce wasting and colitis." (PMID 23840334, 2013). "This pathway also interested us since CXCR6 has been shown to have a role for trafficking of pathogenic T cells in other animal models of autoimmunity such as EAE and colitis." (PMID 30766536, 2019). "We found that 80% of colonic lamina propria CD4+ T cells expressed CXCR6 in the CD45RBhigh T cell-transferred colitis model." (PMID 23840334, 2013). "In accordance with this observation, the majority of LP CD4+ T cells expressed CXCR6 in the mouse model of colitis induced by adoptive transfer of CD4+CD45RBhigh T cells." (PMID 23840334, 2013). "By contrast, retransfer of CXCR6− cells evoked colitis similar to that observed in CD4+CD45RBhigh T cell-transferred mice, and resulted in their conversion into CXCR6+ cells." (PMID 23840334, 2013). "We here report that CD4+ T cells in the inflamed colon of CD4+CD45RBhigh T cell-transferred colitis model can be divided into two subpopulations according to the expression of CXCR6." (PMID 23840334, 2013). "Most CD4+ T cells in colonic LP strongly expressed CXCR6 in colitis model mice at 8 weeks after adoptive transfer." (PMID 23840334, 2013). "Consistent with CXCR6 being the most highly upregulated chemokine, we found that CD69+ CD103+ CXCR6+ CD4+ and CD8+ T cells were expanded in both the cLP and intraepithelial layer in mice with CPI colitis in comparison to control mice." (PMID 37872166, 2023). "In agreement with our findings, we observed increased expression of IFNG, GZMB CXCR6 and CTLA4 in T cell clusters in with patients with CPI colitis patients in comparison with healthy controls." (PMID 37872166, 2023). "To further assess the roles of CXCR6+ and CXCR6− T cells in the pathogenesis of colitis, we next performed adoptive retransfer of LP CXCR6+ and CXCR6− CD4+ T cells recovered from the inflamed colon." (PMID 23840334, 2013). "In germ free mice increased numbers of CXCR6+ iNKT cells are found in colon and lung due to increased CXCL16 expression and both colitis and lung allergic responses are increased." (PMID 23262169, 2013). "Therefore, CXCR6 could well be a functional marker for the Th17-type effector, but that CXCR6 deficiency would not affect the development of colitis in a Th1-dominant model such as the CD4+CD45RBhigh cell-transferred model." (PMID 23840334, 2013). "Additionally, in a Dextran Sulfate Sodium (DSS)-induced colitis model combined with single-cell RNA sequencing, PUT supplementation resulted in the elimination of CXCR6+ CD8+ T cells in the colon." (PMID 41700134, 2026). "In order to determine whether CXCR6 expression on CD4+ T cells relates to an effector function, we performed intracellular cytokine staining on SP, MLN and colonic LP cells from colitis model mice at 8 week post-transfer." (PMID 23840334, 2013). "In addition, it is known that in the pathogenesis of ICI colitis, a prominent role is played by CD8+ T resident memory cells that express high levels of C-X-C chemokine receptor type 6 and 3 (CXCR6/CXCR3), whose ligands (i.e., CXCL9 and CXCL10, respectively) are upregulated by IFN-γ and TNF." (PMID 38339367, 2024). "Retransfer of the LP CXCR6+ cells, however, failed to induce colitis." (PMID 23840334, 2013).
liver fibrosis (10 papers, 2014 to 2025). "The adoptive transfer of wildtype (WT) NKT cells into Cxcr6-deficient mice in a model of steatohepatitis restored inflammation and liver fibrosis." (PMID 25372401, 2014). "In addition, CXCR6 promotes hepatic fibrogenesis, since CXCR6-deficient mice were protected from liver fibrosis progression in two different mouse models." (PMID 24646914, 2014). "Our research confirmed that CXCR6 is substantially expressed in patients with advanced hepatic fibrosis, as evidenced by the analysis of public datasets and human fibrotic liver samples." (PMID 40822973, 2025). "CXCR6 expression was initially analyzed across five publicly available datasets, revealing elevated levels in hepatic fibrosis compared to normal liver tissues." (PMID 40822973, 2025). "WB analysis consistently showed higher protein levels of α-SMA and CXCR6 in the hepatic fibrosis models." (PMID 40822973, 2025). "In conclusion, this study revealed that CXCR6 is upregulated in both human and mouse hepatic fibrosis." (PMID 40822973, 2025). "This study investigates the previously unexplored role of CXC chemokine receptor 6 (CXCR6) in hepatic fibrosis, where excessive extracellular matrix deposition by activated hepatic stellate cells (aHSCs) drives disease progression." (PMID 40822973, 2025). "The strengths of this study are that these in vivo data provide strong evidence for the therapeutic potential of CXCR6 inhibition in hepatic fibrosis." (PMID 40822973, 2025). "To explore the mechanisms underlying the beneficial effects of QGHXR on liver fibrosis, we studied the CXCL16/CXCR6 axis in ethanol plus CCl4-treated mice following QGHXR administration." (PMID 36636609, 2023). "Previous report has demonstrated that CXCL16/CXCR6 signaling pathway promotes the progression of liver fibrosis." (PMID 31379980, 2019). "In this study, CXCR6 was found to be upregulated in hepatic fibrosis." (PMID 40822973, 2025). "Additionally, mRNA levels of fibrosis markers, COL1A1 and TGFB1, were elevated during hepatic fibrosis, alongside an increase in CXCR6 expression." (PMID 40822973, 2025). "Moreover, CXCR6 knockdown alleviated hepatic fibrosis, as indicated by the reduced expression of α-SMA and collagen type I α1 (COL1α1) in vitro." (PMID 40822973, 2025). "Additionally, qPCR analysis of human liver samples further corroborated the increased mRNA levels of α-SMA and CXCR6 in hepatic fibrosis." (PMID 40822973, 2025). "On the other hand, liver NKT cells accumulate in a CXCR6-dependent manner early after injury, exacerbating the inflammatory response and promoting the progression of liver fibrosis, suggesting that the CXCR6/CXCL16 pathway may be an effective target for the treatment of liver fibrosis." (PMID 38846640, 2024). "Thus, targeting CXCR6 may offer a potential therapeutic strategy for hepatic fibrosis." (PMID 40822973, 2025). "WB analysis confirmed the enhanced protein expression of both CXCR6 and α-SMA in advanced stages of hepatic fibrosis." (PMID 40822973, 2025). "CXCR6-expressing NKT cells were found to induce hepatic inflammation and to recruit macrophages resulting in liver fibrosis." (PMID 24646914, 2014). "Our findings position CXCR6 inhibition as a promising therapeutic strategy that uniquely targets both fibrogenesis (through hepatic stellate cell senescence induction) and inflammation (via SASP regulation) in hepatic fibrosis." (PMID 40822973, 2025). "Thus, CCR5, CXCR2, CXCR4 and CXCR6 antagonists or the application of CXCL9 may serve for prevention and treatment of liver fibrosis." (PMID 24646914, 2014).
pancreatic cancer (10 papers, 2016 to 2025). "n a mouse pancreatic cancer model, transduction of CXCR6 into CAR-T cells targeting mesothelin (CART-MSLN) promoted tumor rejection and durable remission." (PMID 41479900, 2025). "Tumor cells and lymphocytes express CXCR6 on their surface and evidence of CXCR6 expression in tumor infiltrating neutrophils was found in patients with pancreatic carcinoma." (PMID 27618112, 2016). "In addition, CAR-T cells targeting pancreatic cancer can enhance their invasion, adhesion and therapeutic effect by overexpressing CXCR6." (PMID 38756774, 2024). "However, further studies on the functionality of CXCR6 in pancreatic cancer tissues are required." (PMID 38335302, 2024). "Other examples include T cells engineered to express the chemokine receptor CXCR5 to improve migration in CXCL13 rich lung as well as head and neck cancer microenvironments, and CXCR6 expression that improved migration and function in hypoxic CXCL16-rich pancreatic tumor milieus." (PMID 41181132, 2025). "Here, we showed that CXCR6 was expressed nine times more in DP CD8+ T cells than in DN CD8+ T cells, which could indicate a relevant function of this chemokine receptor in pancreatic cancer immunosurveillance." (PMID 38335302, 2024). "One study showed that engineering T cells to highly express CXCR6 made these T cells attracted to the CXC chemokine ligand 16 released by pancreatic cancer cells, resulting in enhanced T cell recognition and clearance of pancreatic cancer cells." (PMID 38756774, 2024). "Thus, CAR T cells engineered to express CXCR6 exerted superior anti-tumour activity in pre-clinical models of pancreatic cancer compared to CAR T cells without this genetic modification." (PMID 35464424, 2022).
colorectal cancer (9 papers, 2015 to 2026). A primary or metastatic malignant neoplasm that affects the colon or rectum. "For example, increased infiltration of CD8+ and CD4+ T cells was associated with CXCL16 and its receptor CXCR6 expression in colorectal cancers." (PMID 30774761, 2019). "Similarly, high expression of CXCR6 in colorectal cancer was associated with a good prognosis and positively correlated with the expression of CD8 in tumor." (PMID 36311728, 2022). "For this reason, we screened 7 m6A-related genes (IL12RB1, FASLG, CXCL13, GBP2, CXCL10, CXCR6, and CIITA) through WGCNA and LASSO regression in this study and established an m6A-GPI in colorectal cancer." (PMID 37427112, 2023). "In a mouse model of colorectal cancer, CXCL16 inhibited liver metastasis via recruitment of CXCR6 expressing T cells and iNKT cells." (PMID 27471636, 2016).
psoriasis (9 papers, 2020 to 2025). An autoimmune condition characterized by red, well-delineated plaques with silvery scales that are usually on the extensor surfaces and scalp. "At the same time, CXCR6-expressing T cells are enriched in inflamed tissues of patients with psoriasis and inflammatory arthritis, suggesting a pathogenic role for CXCR6 in these autoimmune diseases." (PMID 39087473, 2024). "Previous studies have shown that in psoriasis, the CXCR6 axis induces CD8+ T cell migration to human skin and promotes the recruitment of T lymphocytes in joint cavities." (PMID 40722833, 2025). "This study integrates multi-omics approaches to reveal the pyroptotic characteristics of psoriasis lesions and suggests that highly pyroptotic MDMs may participate in psoriasis pathogenesis through the CXCL16/CXCR6 signaling axis." (PMID 40722833, 2025). "The finding demonstrating a reduced percentage of CXCR6 expressing ILCs in blood of patients with psoriasis compared with healthy controls might further support the concept of an active recruitment of CXCR6+ cells to peripheral sites." (PMID 35784287, 2022). "The expression of CXCR6 on ILCs was elevated in psoriasis patients." (PMID 35784287, 2022). "Indeed, when we analyzed the percentage of peripheral ILCs expressing the receptor CXCR6 on their surface, the numbers were reduced in patients with psoriasis." (PMID 35784287, 2022). "CXCR6+ CD8+ T cells are found in the dermis and epidermis in psoriasis but not atopic dermatitis skin lesions." (PMID 37131254, 2023).
renal fibrosis (9 papers, 2012 to 2025). A final common manifestation of a wide variety of chronic kidney diseases characterized by glomerulosclerosis and tubulointerstitial fibrosis. "Intestinal ILC3s migrate to the kidney through CXCL16/CXCR6 axis and IL‐17A derived from ILC3s in PD‐1‐dependent manner promotes renal fibrosis." (PMID 40801800, 2025). "Targeted disruption of CXCL16 prevented the development of renal fibrosis by suppressing the recruitment of CXCR6-expressing bone marrow-derived fibroblast precursors, macrophages and T cells into the kidney and myofibroblast formation." (PMID 33552057, 2020). "Recent work has identified CXCL16-CXCR6 signaling as the mediator of group 3 innate lymphoid cell accumulation in the kidney during renal fibrosis and chronic kidney disease, supporting a function of CXCR6 in kidney immune responses during persistent/chronic inflammation." (PMID 40043065, 2025). "A previous study demonstrated that the CXCL16 signaling pathway contributes to the renal injury in diabetic nephropathy mouse model and CXCR6 regulates the collagen deposition and expression of collagen I and fibronectin through recruitment of bone marrow derived fibroblast in renal fibrosis." (PMID 33922243, 2021). "To determine the role of CXCR6 in renal fibrosis, we stained the kidney sections with sirius red." (PMID 31924817, 2020). "Moreover, CXCL16/CXCR6 has contributed to the pathogenesis of renal fibrosis." (PMID 31379980, 2019). "More recently, our studies reported that CXCL16 binding to its receptor CXCR6 activates PI3 kinase γ to recruit myeloid fibroblasts into the kidney, contributing to the development of renal fibrosis." (PMID 34831280, 2021).
rheumatoid arthritis (9 papers, 2013 to 2025). A chronic, systemic autoimmune disorder characterized by inflammation in the synovial membranes and articular surfaces. "Murine and translational studies suggested that CXCR3 and CXCR6 are key elements for effector T cells to migrate into the joints in rheumatoid arthritis, and MDX-1100, anti-CXCL10 monoclonal antibody, showed clinical efficacy in rheumatoid arthritis." (PMID 35413951, 2022). "CXCR6/CXCL16 is highly expressed in the synovial tissue of rheumatoid arthritis (RA) patients, where it recruits T cells and monocytes to the inflamed joints, promoting the production of pro‐inflammatory cytokines that exacerbate joint inflammation and damage." (PMID 41291399, 2025). "In a murine rheumatoid arthritis model, CXCL16/CXCR6 signaling has been reported to have a central role in endothelial progenitor cell chemotaxis and angiogenesis." (PMID 31527616, 2019). "Previous studies have linked CXCR6 expression by CD4+ and CD8+ T cells to IFN-γ but not IL-4 expression in graft-versus-host-induced hepatitis and rheumatoid arthritis." (PMID 23840334, 2013).
vitiligo (9 papers, 2019 to 2025). Generalized well circumscribed patches of leukoderma that are generally distributed over symmetric body locations and is due to autoimmune destruction of melanocytes. "Under the promoted CXCL16 production, the cutaneous infiltration of CXCR6+ CD8+ T cells was increased in vitiligo perilesional skin, leading to melanocyte loss in vitiligo lesions." (PMID 35096274, 2022). "CXCL16 can be secreted from keratinocytes, dendritic cells, and even Langerhans cells, and functions as a chemokine by binding to its receptor CXCR6 to mediate homing of CD8 + T cells in vitiligo skin." (PMID 40361040, 2025). "Alternatively, CXCL16 secreted by CD11c+ cells may continuously recruit CD8 TRM cells to the clusters and areas of vitiligo through CXCR6." (PMID 34362825, 2021). "Alternatively, CXCR6 may be required for establishing or disseminating areas of vitiligo." (PMID 34362825, 2021). "In patients with vitiligo, the overexpression of chemokine receptors of the CXC family has been reported, namely CXCR3 and CXCR6, as well as the chemokines CXCL9, 10, and 11, natural ligands of CXCR3, and CXCL16, the only known natural ligand of CXCR6." (PMID 32992956, 2020). "As gene analysis on cells isolated from lesional and nonlesional skin of vitiligo has identified CXCL16 and CXCR6 in the pathogenesis of the disease, the role of the CXCL16-CXCR6 axis in vitiligo is better appreciated in recent studies." (PMID 35096274, 2022).
viral infection (8 papers, 2012 to 2025). "The first approach subdivides activated CD4+ T cells into CXCR6+CXCR5- Th1-like cells and CXCR6-CXCR5+ Tfh-like cells at the peak of immune response during viral infection." (PMID 40391228, 2025). "In viral infections or persistent inflammation, the CD56bright NK subpopulation preferentially homes to these sites via chemokine receptors (CXCR3, CCR5, and CXCR6), which detect localized inflammatory cues." (PMID 40497938, 2025). "CXCR6 has been shown to play an important role in the localization and retention of TRM cells in the liver and lungs after viral infection." (PMID 36153630, 2022). "Our analysis specifically indicates the involvement of CXCR6, PIK3CB, and OSMR in the regulation of the RIG-I-like receptor signaling pathway, a common immune signaling pathway crucial for innate immunity, inflammation, and the upregulation of antiviral proteins to control viral infections." (PMID 39148025, 2024). "In this study we found that CCR5 and several other chemokine receptors which support viral infection, such as CCR8 and CXCR6 are either absent or demonstrate markedly different expression levels in macrophage-like cell lines compared with primary AMs." (PMID 23102269, 2012).
liver disease (7 papers, 2018 to 2024). "In conclusion, this study demonstrates that bystander-activated CXCR6+CD69+ CD8+ T cells are abundant in the ascites of patients with decompensated cirrhosis and are associated with liver disease severity." (PMID 38882602, 2024). "This was further corroborated by correlations of IFNγ production of peritoneal CD8+ T cells and peritoneal CXCR6+CD69+ CD8+ T cells with markers of liver disease severity and renal impairment." (PMID 38882602, 2024). "Of note, IFNγ production by ascites CD8+ T cells correlated with markers of liver disease severity, and this was also true for the CXCR6+CD69+ CD8+ T-cell subset." (PMID 38882602, 2024). "We also found that HBV-infected livers contained more infiltration of CXCR6+ LrT and LrNK cells, indicated a potential role of LrNK & LrT cells in the pathogenesis of HBV-associated liver diseases." (PMID 32351704, 2020). "In both liver disease groups, CXCR6 and CD49a were found more frequently on CD56bright and CD56dim NK cells as compared to HC." (PMID 31803181, 2019). "Remarkably, the frequencies of ascites CXCR6+CD69+ CD8+ T cells were significantly correlated with markers of liver disease severity, as indicated by the model for end-stage liver disease score, Child–Pugh score, bilirubin blood levels, and international normalized ratio." (PMID 38882602, 2024). "It is therefore important to understand how NK cells expressing tissue‐resident markers CXCR6+ and CD49a+ are influenced by cytokines as this may impact liver disease." (PMID 28952190, 2018). "While additional research is required to better define the exact mechanism by which CXCR3+CXCR6+ γδT cells exert their protective role, findings from the current study provide more insight into liver-resident lymphocytes and provide novel strategies for the treatment of diverse liver diseases." (PMID 35126348, 2021). "•Co-expression of CXCR6 and CD69 identifies distinct clusters of CD8+ T cells that correlate with liver disease severity." (PMID 38882602, 2024). "However, human LrNK cells remain challenging to identify, for example, CD49a+ CD56bright NK cells, CXCR6+ NK cells and CD49e− NK cells, so that the roles of LrNK cells in chronic HBV infection and related liver disease are elusive." (PMID 38793619, 2024).
nonalcoholic steatohepatitis (7 papers, 2022 to 2024). "The gene expression signature of these CXCR6+ CD8+ T cells approximates those of tissue-damaging CXCR6+ CD8+ T cells in nonalcoholic steatohepatitis." (PMID 35401519, 2022). "Likewise, non-specific CXCR6+CD8+ TRM cells bearing similar functional features in non-alcoholic steatohepatitis (NASH) mice and patients with NASH kill hepatocytes through P2X7 purinergic receptors, but not through MHC class I recognition." (PMID 39193473, 2024).